PER1 (period circadian regulator 1)
Diseases named in the same sentence as PER1 in open-access papers (continued):
Sharing a sentence is not in itself a finding about the gene and the disease.
Alzheimer disease (6 papers, 2021 to 2025). A progressive, neurodegenerative disease characterized by loss of function and death of nerve cells in several areas of the brain leading to loss of cognitive function such as memory and language. "Furthermore, PER1 genotypes (e.g., AG carriers of the risk allele G) have been associated with depressive states and altered white matter integrity, which may manifest as comorbid symptoms in neurodegenerative diseases such as Alzheimer’s disease (AD)." (PMID 41451215, 2025). "Similarly, the rhythmic expression of specific sleep genes (BMAL1, CRY1, and PER1) is also found to be disturbed in neurodegenerations such as mild cognitive impairment (MCI) and Alzheimer’s disease (AD) dementia." (PMID 35052403, 2021).
bipolar disorder (6 papers, 2010 to 2025). A disorder of the brain that causes unusual shifts in mood, energy, activity levels and the ability to carry out day-to-day tasks. "Several core clock genes, such as PER1, PER3, CRY1, and CRY2, have been found to be associated with bipolar disorder." (PMID 39454958, 2024). "Phase control through the melatonin-guided interval of Per1/Per2 to Cry1/Cry2 expression peaks may have relevance to mood disorders, as the internal alignment and the melatonin signal (amplitude and phase) are abnormal in patients with bipolar disorder and those with winter depression in particular." (PMID 20195522, 2010).
cholangiocarcinoma (6 papers, 2017 to 2025). A carcinoma that arises from the intrahepatic biliary tree (intrahepatic cholangiocarcinoma) or from the junction, or adjacent to the junction, of the right and left hepatic ducts (hilar cholangiocarcinoma). "Research has also confirmed that Per1, as a target of miR‐34a, is involved in suppressing the growth and invasion of cholangiocarcinoma." (PMID 41143275, 2025). "In cholangiocarcinoma, PER1 overexpression suppresses cell proliferation by upregulating cell cycle regulators (e.g., WEE1, CREB phosphatase 1, CRE-BP1), increasing the proportion of G2/M and S phase cells, and reducing G1 phase cell populations." (PMID 41451215, 2025). "miR-34a targets Per1 and is rhythmically expressed in cholangiocarcinoma cells and H69 cells, and its inhibition decreases proliferation, migration and invasion in cholangiocarcinoma cells." (PMID 31799078, 2019). "Reduced Per1 expression tends to lead to malignant phenotypes in cholangiocarcinoma." (PMID 41143275, 2025). "In addition, Han59 found that miR-34a reduced the likelihood of cholangiocarcinoma in human cells through its action on PER1." (PMID 34394254, 2020). "In cholangiocarcinoma, PER1 expression is decreased and periodical rhythm is lost." (PMID 34394254, 2020).
sleep disorder (6 papers, 2022 to 2025). A change from the patient's baseline sleeping pattern, in the hours slept and/or an alteration/dysfunction in the stages of sleep. "Reductions in the risk alleles for sleep disorders PER1 and NR1D1 were found to have a significant impact on the risk of haemorrhagic stroke in one study." (PMID 41245864, 2025).
liver cancer (5 papers, 2013 to 2024). An epithelial or non-epithelial malignant neoplasm that arises from the liver. "On this premise, a candidate tumor suppressor role for PER1 in liver cancer should be carefully evaluated in the context of a lack of macroH2A1 histones, but at the same time could represent a potential molecular target with implications for therapeutic strategies." (PMID 34440260, 2021). "Conversely, the expression levels of ARNTL, NR1D1, PER1, PER2, PER3, PRKAG2, and RORA were not significantly related to the OS of liver cancer patients." (PMID 34149816, 2021).
lymph node metastasis (5 papers, 2013 to 2021). "PER1 is decreased in squamous cell carcinoma and low expression of PER1 is closely related to unfavorable clinical behavior, such as developed lymph node metastasis and advanced clinical stage, and poor survival." (PMID 34069297, 2021). "The difference had statistical significance (P<0.05); PER1 protein expression was significantly up-regulated in patients of T1∼T2 staging and those without lymph node metastasis compared to that of T3∼T4 staging and those with lymph node metastasis(P<0.05), respectively." (PMID 23405233, 2013). "Our previous clinical research revealed that PER1 expression is decreased in OSCC and closely correlated with clinical phase and lymph node metastasis in patients with OSCC." (PMID 26943040, 2016).
metabolic syndrome (5 papers, 2009 to 2025). A cluster of metabolic risk factors for CARDIOVASCULAR DISEASES and TYPE 2 DIABETES MELLITUS. "Clock genes are linked directly to metabolic syndromes; polymorphisms circadian clock genes CLOCK, BMAL1, Per1/2 and Cry1/2 have been associated with metabolic disorders, including neuropsychiatric or neurodegenerative diseases." (PMID 33184471, 2020). "One of the most correlated PER1 genes in the adipose was ZNF145 (also known as PLZF), which drives metabolic syndrome in rats and affects the transcription of the prorenin/renin receptor." (PMID 19203388, 2009).
non-small cell lung carcinoma (5 papers, 2015 to 2024). A group of at least three distinct histological types of lung cancer, including non-small cell squamous cell carcinoma, adenocarcinoma, and large cell carcinoma. "In non-small-cell lung cancer, mangiferin inhibits lipopolysaccharide-induced epithelial–mesenchymal transition and enhances the expression of PER1." (PMID 34220965, 2021).
oral cancer (5 papers, 2019 to 2025). "Aberrant expression of Per1 affects the pathological process of oral cancer by controlling the expression of matrix metalloproteinase-2 and the intracellular distribution of laminin receptors, Per1 deficiency via the AKT/mTOR pathway promotes OSCC progression." (PMID 36467684, 2022). "Salivary exosomal miR-24-3p promotes the proliferation of oral cancer cells by targeting period circadian regulator 1 (PER1)." (PMID 36612314, 2023). "In addition, PER1 was reported to get involved in glycolysis and glucose uptake in oral carcinoma, which in turn regulate cell viability by targeting RACK1-based complex." (PMID 35140788, 2022). "The specific mechanism is as follows: the core clock gene Period 1 (PER1) can inhibit glycolysis-mediated cell proliferation by forming the PER1/RACK1/PI3K complex, thereby suppressing the progression of oral cancer cells." (PMID 40282437, 2025).
atherosclerosis (4 papers, 2014 to 2024). A disease characterized by the build-up of fatty material and calcium deposition in the arterial wall resulting in partial or complete occlusion of the arterial lumen. "The transplantation of arteries from Per1/2−/− mice to wild type mice leads to the development of atherosclerosis in the transplanted graft, which suggests the important role of peripheral PER1/2 in the vascular system." (PMID 33445491, 2021). "Treatment with S100A8, a novel adipocytokine associated with visceral fat accumulation and atherosclerosis, did not alter Per1 mRNA level in 3T3-L1 adipocytes." (PMID 25397888, 2014). "In this study, we revealed that RORB, RORC, PER1, CRY1, FTO were in close relationship with atherosclerosis, particularly in atherosclerotic lesions with higher immune infiltration." (PMID 34082770, 2021). "All the available evidence suggests that chronopharmacology-based therapy targeting RORB, RORC, PER1, CRY1, or FTO might constitute another approach for the treatment of atherosclerosis." (PMID 34082770, 2021).
autism (4 papers, 2022 to 2023). Persistent deficits in social interaction and communication and interaction as well as a markedly restricted repertoire of activity and interest as well as repetitive patterns of behavior. "Moreover, a study on the hypothesis that clock genes are implicated in autistic disorder revealed noteworthy associations in the PER1 and NPAS2 genes." (PMID 37807632, 2023). "Therefore, the rescuing effect of Tau reduction on autism-like phenotypes in Fmr1 KO mice is unlikely through reversing Per1 expression and periodic activity defect." (PMID 37936174, 2023).
colitis (4 papers, 2022 to 2025). Inflammation of the colon. "Goblet cells produce a protective mucus in the intestine, and previous studies have shown that there are fewer goblet cells present in Per1/2 mutant mice which predisposes these to colitis." (PMID 35223537, 2022). "This seems to contradict the findings of previous studies showing that mice with global knockout of the circadian genes Bmal1, Per1/2, or Rev-erbβ exhibit more severe symptoms in experimental colitis." (PMID 40307620, 2025). "Recent studies have shown that disrupting genetic components of the circadian clock mechanism including the genes Per1/2, Nr1d1, and Rorα result in increased colitis severity." (PMID 35223537, 2022). "We also compared the expression of several key circadian genes including Arntl, Clock, Cry1, Cry2, Per1, Per2, Per3, Nr1d1, and Npas2 in colon samples collected at 03, 09, 15, and 21 of normal mice, colitis mice, normal mice receiving BBR, and colitis mice receiving BBR." (PMID 36528592, 2022). "Likewise, significantly reduced numbers of secretory Paneth cells, goblet cells and lysozyme were detected in colitis-affected mice without Per1/2." (PMID 37218867, 2023).
head and neck squamous cell carcinoma (4 papers, 2016 to 2024). A squamous cell carcinoma that arises from any of the following anatomic sites: lip and oral cavity, nasal cavity, paranasal sinuses, pharynx, larynx, and salivary glands. "Patients with advanced-stage head and neck squamous cell carcinoma exhibited markedly lower levels of PER1, PER2, and PER3 proteins compared to those with early-stage tumors, and higher levels of these proteins were associated with longer overall and recurrence-free survival." (PMID 38813085, 2024).
insomnia (4 papers, 2020 to 2025). A sleep disorder characterized by difficulty in falling asleep and/or remaining asleep. "While insomnia has been associated with decreased expression of PER1, acute DS may increase its expression." (PMID 41516251, 2025). "In healthy controls, insomnia severity correlated with evening expression of BMAL1, PER1, and CRY1." (PMID 39201748, 2024).
leukemia (4 papers, 2015 to 2023). A malignant (clonal) hematologic disorder, involving hematopoietic stem cells and characterized by the presence of primitive or atypical myeloid or lymphoid cells in the bone marrow and the blood. "PER1/2/3, BMAL1, CLOCK, REV-ERBα, and PPARα were downregulated in all types of leukemia, suggesting their potential role in leukemic development." (PMID 35897788, 2022).
lung adenocarcinoma (4 papers, 2021 to 2025). A carcinoma that arises from the lung and is characterized by the presence of malignant glandular epithelial cells. "In the Cancer Genome Atlas Lung Adenocarcinoma (TCGA LUAD) dataset, we found that, within KRAS-mutant tumors, those with STK11 mutations had higher PER1 mRNA expression (p = 0.0224) than those with wildtype LKB1." (PMID 40715535, 2025). "In the current study, we use retrospective analysis of human cancer transcriptomic and clinical data in combination with functional studies in human cell models to investigate the significance of altered PER1 expression in LKB1-mutant lung adenocarcinoma." (PMID 40715535, 2025). "This study characterizes the functional effects and clinical characteristics of high PER1 mRNA and high PER1 protein expression in treatment resistant lung adenocarcinoma." (PMID 40715535, 2025). "A possible explanation for this is the reciprocal regulation between PER1 and HIF1α, a potential role for HIF3α, or that hypoxia has context specific roles in molecular subsets of lung adenocarcinoma." (PMID 40715535, 2025). "PER1 mRNA and protein are upregulated in STK11-mutant lung adenocarcinoma tumors and STK11-knockout human bronchial epithelial cells (HBEC3-KT)." (PMID 40715535, 2025).
mood disorder (4 papers, 2010 to 2022). A cognitive disorder a disturbance in which the person's mood is hypothesized to be the main underlying feature. "Several studies suggested that an impaired circadian system, regulated by a network of “clock genes,” contributes to the etiology and symptomatology of mood disorders, highlighting an association between mutations at the level of clock genes such us Clock or Per1-3 and variations in mood." (PMID 25638817, 2015).
advanced sleep phase syndrome (3 papers, 2016 to 2021). A very rare circadian rhythm sleep disorder characterized by very early sleep onset and offset possibly resulting in emotional and physical disruptions. "To analyse Per1-Per2 cooperative roles at the cell culture level, we established a Per2 knockout-rescue system, which can detect period shortening in a familial advanced sleep phase syndrome (FASPS) mutant." (PMID 27609640, 2016). "PER1 and PER2 were reported to be associated with advanced sleep phase syndrome in a British population, but not in a Japanese family." (PMID 33412754, 2020).
alcohol use disorder (3 papers, 2016 to 2024). "Clinical investigations report reduced baseline Clock mRNA levels in patients with alcohol use disorder, as well reduced baseline mRNA levels of circadian proteins BMAL1, Per1, Per2, Cry1, and Cry2." (PMID 35456507, 2022).
asthma (3 papers, 2015 to 2025). "Through machine learning and bioinformatics techniques, four hub genes, including HIF1A, NNMT, OCRL, and PER1, were identified as potential markers associated with asthma metabolism, especially HIF-1A." (PMID 36676950, 2022). "In this study, four hub genes including HIF1A, OCRL, NNMT, and PER1 were identified as potential markers associated with asthma metabolism by bioinformatics analysis." (PMID 36676950, 2022). "Additionally, one 2-DE spot was detected as PER1 which is a confirmed wheat allergen likely associated with Baker’s asthma." (PMID 26124766, 2015). "In the present study, we merged the differentially expressed genes (DEGs) of asthma in the GEO database with the metabolic genes obtained by Genecard for bioinformatics analysis and successfully screened out the metabolism-related hub genes (HIF1A, OCRL, NNMT, and PER1)." (PMID 36676950, 2022).
chronic myeloid leukemia (3 papers, 2010 to 2019). "The expression of Per1, Per2, Per3, Cry1, Cry2, and Bmal1 is significantly impaired in both chronic phase and blast crisis of chronic myeloid leukemia (CML) samples compared with those in normal samples." (PMID 20353609, 2010). "Decreased expression of PER1/2/3 (and CRY1/2 and BMAL1) has also been observed in the blood of patients with chronic myeloid leukemia (CML) when compared to the blood of healthy individuals." (PMID 33089179, 2019). "It has been demonstrated that the expression levels of the human CRY1, CRY2, PER1, PER2, PER3, and BMAL1 genes were down-regulated in both the chronic phase and blast crisis in chronic myeloid leukemia (CML)." (PMID 26253128, 2015).
endometrial carcinoma (3 papers, 2011 to 2021). A malignant tumor arising from the epithelium that lines the cavity of the uterine body. "Rhythm-related factors PER1, TUBB2B, and tumor immune factors can regulate the pathogenesis and progression of endometrial cancer." (PMID 34220965, 2021).
esophageal squamous cell carcinoma (3 papers, 2019 to 2022). Esophageal squamous cell carcinoma (ESCC) is a type of esophageal carcinoma (EC) that can affect any part of the esophagus, but is usually located in the upper or middle third. "SULT2B1 can inhibit the proliferation of esophageal squamous cell carcinoma (ESCC) cells, and the hypermethylation of its promoter can promote the progression of esophageal tumor by downregulating PER1." (PMID 35628460, 2022). "Their result showed that the expression of clock genes PER1 and PER2 were decreased significantly in esophageal squamous cell carcinoma (ESCC) tumors with different proliferation, differentiation and different TNM stage." (PMID 31151182, 2019).
Glucose intolerance (3 papers, 2025). Glucose intolerance (GI) can be defined as dysglycemia that comprises both prediabetes and diabetes. "Specifically, research has shown that the sleep-loss-induced hypermethylation of the clock genes Period Circadian Protein Homolog 1 (PER1) and Cryptochrome 1 (CHRY1) contributes to glucose intolerance." (PMID 40700251, 2025).
Hyperglycemia (3 papers, 2022 to 2025). An increased concentration of glucose in the blood. "In OSA with hyperglycemia (fasting glucose ≥6.1 mmol/L) patients, mRNA levels of Dec1 were higher (p < 0.05), and those of Per1 were lower (p < 0.001) than those of OSA without hyperglycemia patients (fasting glucose<6.1 mmol/L)." (PMID 36105285, 2022).
lymphoma (3 papers, 2010 to 2021). A malignant (clonal) proliferation of B- lymphocytes or T- lymphocytes which involves the lymph nodes, bone marrow and/or extranodal sites. "Consistently, mice homozygous for the mPer2m/m mutation show an increased sensitivity to radiation and a higher risk to develop lymphoma, while PER1 is involved in the regulation of proapoptotic signals." (PMID 33810377, 2021).
sarcopenia (3 papers, 2021 to 2025). Progressive decline in muscle mass due to aging which results in decreased functional capacity of muscles. "Genes with inconsistent directions, Per1, Shisal2b, AW551984, and those located in the second and fourth quadrants of the LogFC vs. correlation plot, were considered less likely to be directly involved in sarcopenia." (PMID 40869189, 2025).
schizophrenia (3 papers, 2017 to 2024). A major psychotic disorder characterized by abnormalities in the perception or expression of reality. "The expression of Per1 mRNA in the temporal lobe in individuals with schizophrenia decreases significantly compared with age-matched healthy controls." (PMID 28468274, 2017). "Indeed, compared with healthy controls, schizophrenia patients presented disruptions in diurnal rhythms of the expression of Per1, Per3, and Npas2, accompanied by a delayed phase in the expression of Per2 and by a decreasing in Per3 and Npas2 expression." (PMID 28468274, 2017). "In schizophrenia (SCH), clock gene disruption has been demonstrated for CRY1 and PER2 in skin fibroblasts, PER1/2/3 and NPAS2 in white blood cells, and in post-mortem analyses for PER1/2, CRY2, and NR1D1 in the prefrontal cortex." (PMID 38976708, 2024).
Sepsis (3 papers, 2012 to 2025). Sepsis is defined as life-threatening organ dysfunction caused by a dysregulated host response to infection. "A similar phenomenon occurs in the hippocampus and microglia of adult Sprague-Dawley male rats for Clock, Bmal1, Per1/2, and Rev-Erb-α in response to lipopolysaccharide (LPS)-induced sepsis." (PMID 39968295, 2025). "The rhythmicity of Bmal1, Per1/2, Cry1, Rev-Erb-α, and Rev-Erb-β in whole-blood is lost in patients with sepsis or septic shock, likely reflecting the changes in immune cells." (PMID 39968295, 2025). "It is also not clear why there was a significant effect of prior sepsis on PER2, but not PER1 in the SCN, although modulation through different signalling mechanisms may be a factor here." (PMID 23071720, 2012).
squamous cell carcinoma (3 papers, 2013 to 2022). A carcinoma arising from squamous epithelial cells. "In line with our observation, previous studies have shown that PER1 is able to inhibit Akt/mTOR signalling, although in squamous cell carcinoma, and plays a role in the regulation of cytokine expression, such as IFNG, in NK cells." (PMID 35143696, 2022). "Abnormal expression of the clock gene PER1 shows a correlation with the tumorigenesis of squamous cell carcinoma." (PMID 34069297, 2021).